RPS10P7 (ribosomal protein S10 pseudogene 7)
Synonyms: lnc-MCEI
Gene: Transcribed processed pseudogene on chromosome 1 (201,520,056 to 201,520,549, forward strand). Ensembl gene ENSG00000223396.
Diseases named in the same sentence as RPS10P7 in open-access papers:
RPS10P7 is named in the same sentence as 2 diseases in open-access papers, as found by Europe PMC text mining. Sharing a sentence is not in itself a finding about the gene and the disease.
RPS10P7 shares sentences with these, for which no sentence is quoted: fibroids (2 papers); tumor (1).